PTH (parathyroid hormone)
Diseases named in the same sentence as PTH in open-access papers (continued):
Sharing a sentence is not in itself a finding about the gene and the disease.
Hypercalcemia (continued). "Evaluation of hypercalcemia begins with assessment of serum levels of calcium, ionized calcium, PTH, PTHrP, and 1,25-dihydroxyvitamin D. In the setting of paraneoplastic hypercalcemia, laboratory results reveal increased calcium levels, low-to-normal PTH levels, and unusually high PTHrP." (PMID 37670372, 2023). "Moreover, PTH/Svol exhibited a notable ability in forecasting marked hypercalcemia." (PMID 37892003, 2023). "Moreover, vitamin D replacement in subjects with PHPT and coexistent vitamin D deficiency reduce serum PTH significantly without causing hypercalcemia and hypercalciuria in patients with mild and moderate hypercalcemia." (PMID 37465121, 2023). "Using a reduced dose of PTH may be helpful in preventing hypercalcemia and hypercalciuria." (PMID 37335755, 2023). "The hypercalcemia observed with lanthanum carbonate treatment is hypothesized from the fact that phosphorus reduction raises calcium levels via increasing calcemic action of PTH." (PMID 36827665, 2023). "Hypercalcemia and hypercalciuria may occur due to reduced use of calcium in bone mineralization, resulting in nephrocalcinosis and reduced levels of parathyroid hormone (PTH)." (PMID 37249457, 2023). "However, a possible pathogenetic mechanism has been hypothesized only for obesity, as PTH-induced hypercalcemia could be responsible for the decrease in adipocyte lipolysis." (PMID 36773188, 2023). "Even after the follow-up appointment, we could not identify a causal disease for her PTH-independent hypercalcemia." (PMID 35745247, 2022). "Therefore, hypercalcemia malignancy suspicion was intensified by identifying parathormone (PTH) suppression, in addition to light-chain screening with a positive monoclonal gammopathy and a bone biopsy with 60% of clonal plasma cells receiving a diagnosis of multiple myeloma with an ominous outcome." (PMID 35664896, 2022). "Similarly, pooled data showed a nonsignificant difference in relative risk for hypercalcemia between patients taking PTH therapy and controls (RR = 3.98; 95% CI, 0.77 to 20.55; p = 0.099; I2 = 56.5%; p = 0.130)." (PMID 35485213, 2022). "The hypercalcemia may result from the extended serum half-life of PTH-Fc." (PMID 36172011, 2022). "In addition, biochemical tests may also show hypercalcemia, hyperphosphatemia, hypercalciuria, and a secondary reduction in parathormone (PTH) levels." (PMID 35453912, 2022). "Among those without PTH levels available, 55 183 (68.9%) had other potential causes for hypercalcemia, whereas 24 905 (31.1%, or 18.4% of the entire cohort) lacked another explanation for hypercalcemia and had no diagnosis of PHP." (PMID 36574247, 2022). "Neonates with JMC have severe, but largely asymptomatic hypercalcaemia, hypophosphatemia, hyperphosphaturia, elevated circulating levels of 1,25-dihydroxyvitamin D3, elevated serum alkaline phosphatase, and low or undetectable levels of PTH and PTH-related peptide (PTHrP)." (PMID 33990852, 2022). "There are no specific tumor markers for PC, nor for DTC, but in the case of PC malignancy it could be suspected in patients with severe hypercalcemia (>14 mg/dL or 3.5 mmol/L) and/or with marked PTH elevations (>5–10 times the upper normal limit or absolute levels >500 mg/dL)." (PMID 36143862, 2022). "Selective VDRA vitamin D analogs such as paricalcitol (19‐nor‐1,25‐dihydroxy vitamin D2) and maxacalcitol (22‐oxa‐1,25‐dihydroxy vitamin D3) can reduce PTH levels better than calciferol without increasing the serum calcium concentration; however, it can cause hypercalcemia in some SHP patients." (PMID 34408941, 2021). "However, elevation of PTH level and hypercalcemia progressed." (PMID 33858470, 2021). "Moreover, in two past randomized trials of VDRA in CKD patients, the use of VDRA showed a decrease in PTH but no change in cardiovascular end points with an increased risk of hypercalcemia." (PMID 34853790, 2021).
Hypercalcemia (continued). "While functionally this hypothesis seemed likely, clinically this did not prove to be true based on differences in the clinical presentation of patients with hypercalcemia due to cancer vs. those with hypercalcemia due to known PTH excess syndromes like primary hyperparathyroidism." (PMID 33828987, 2021). "A meta-analysis reported that vitamin D supplementation in patients with PHPT and vitamin D deficiency could significantly reduce PTH levels without causing hypercalcemia and hypercalciuria, indicating it is an effective and safety treatment in PHPT condition." (PMID 34925241, 2021). "Regarding PTH levels before KTx, the majority of patients in group A showed high levels of PTH (pre-transplant hyperparathyroidism) compared with group B. Some authors also show that pre-transplant hyperparathyroidism is correlated with persistent hyperparathyroidism and hypercalcemia post-KTx." (PMID 33909856, 2021). "Although non-PTH-dependent hypercalcemia in individuals with acromegaly is logical in theory and patients often have mild hyperphosphatemia and hypercalciuria, clinically significant hypercalcemia is rare, possibly because of the strong capacity to self-regulate serum calcium." (PMID 33933067, 2021). "Indeed, a post hoc analyses highlighted cinacalcet significantly reduced progression of SHPT to “severe unremitting” HPT (defined as two consecutive PTH values over 1,000 pg/mL, hypercalcemia, the use of cinacalcet with hypercalcemia, or patients requiring PTX)." (PMID 33062583, 2020). "If adverse clinical signs/symptoms continue and further treatment is needed, the approach depends on whether the hypercalcemia is considered to be caused by excess PTH or is of non-parathyroid origin (if feasible to have been elucidated)." (PMID 32396134, 2020). "However, it was concluded that hypercalcemia causes the production of a hormone which reduces the blood calcium level and does not inhibit the production of PTH." (PMID 32963524, 2020). "While some degree of parathyroid hormone (PTH) elevation is considered necessary to maintain normal bone turnover, about 10–20% of dialysis patients have excessively high PTH levels associated with high turnover bone disease, fractures, hypercalcemia episodes and increased mortality." (PMID 31848883, 2020). "An exacerbation of hypercalcemia in subjects with PHP occurred on normalization of serum 25OHD levels following the administration of vitamin D2, probably caused by a further rise in serum 1,25(OH)D levels via increased generation induced by persistently elevated circulating PTH." (PMID 33210066, 2020). "As for hypercalcemia, this syndrome develops due to the protein related to the parathyroid hormone-related peptide (PTHrP) released by the tumor, stimulating bone resorption and leading to higher levels of serum parathyroid hormone (PTH) and osteoclast hyperactivity." (PMID 31035457, 2019). "Therefore, it remains unproven whether PTH-rp hypersecretion was (at least partially) responsible for the hypercalcemia in this case." (PMID 28977163, 2017). "Additionally, we have analysed the patients of PTH-dependent hypercalcemia in the study." (PMID 28687737, 2017). "Additionally, this serves as a reminder that not all PTH-independent hypercalcemia necessarily requires the appearance of fully suppressed PTH levels, particularly in the context of CKD-associated chronic hyperparathyroidism." (PMID 27683096, 2016). "However, it is not clear whether hyperparathyroidism disturbs platelet function and if so whether it is related to the high PTH levels per se or to the accompanying hypercalcemia." (PMID 26377856, 2016). "As tumoral calcinosis resolves, release of soft tissue calcium into the general circulation may cause severe, relative PTH-independent hypercalcemia that is transient and may be observed without apparent harm to the patient, as was demonstrated in this case." (PMID 27683096, 2016).
Hypercalcemia (continued). "However, if the calcium level was 8.0 mg/dl this level of PTH would be normal, this might explain the hypercalcemia and low normal phosphorus found in the exposed group despite their apparently normal PTH serum level." (PMID 27335606, 2016). "Therefore, we could not determine any of the metrics of pHPT severity, including actual PTH values, the degree of hypercalcemia, hypophosphatemia or hypomagnesemia, bone density or the burden of nephrolithiasis." (PMID 27529699, 2016). "Moreover, parathyroid hormone (PTH) and teriparatide lead to hypercalcemia." (PMID 28058134, 2016). "However, when the hypercalcemia is PTH-mediated, surgery is the standard therapy when possible." (PMID 26213611, 2015). "We conclude that hypercalcaemia may result from the overproduction of PTHrP in patients with CAKUT and adequately suppressed PTH, and that hypercalcaemia secondary to PTHrP in children with CAKUT, particularly when they have an element of obstruction, may be under-recognized." (PMID 26019888, 2015). "Higher rate of post-operative elevated PTH might be the consequence of intentional subtotal parathyroidectomy in patients with renal failure, and the subset of four patients with hypercalcemia in our analysis underwent only partial resection of parathyroid tissue, too." (PMID 26079132, 2015). "In this presented case, SLE was stable and could be safely ruled out as a major cause of hypercalcemia because PTH level was very high and serum calcium;eve; normalized soon after surgery." (PMID 25755881, 2015). "Furthermore, the combination of hypercalcemia, normal serum concentration of 25-hydroxyvitamin D, elevated 1,25-dihydroxyvitamin D, and a suppressed parathyroid hormone would indicate an abnormal 1,25-dihydroxyvitamin D production with possible increased intestinal absorption of calcium." (PMID 26635987, 2015). "There may also be important differences between paricalcitol, a selective vitamin D receptor agonist, and the nonselective calcitriol regarding PTH-lowering, risk of hypercalcemia and overall survival." (PMID 24930018, 2014). "We considered they might be mild hypercalcemia and mild deficiency of vitamin D. Changes in circulating calcium concentrations alter PTH secretion via a negative feedback system." (PMID 24959365, 2014). "Furthermore, a suppression of PTH secretion by 1,25(OH)2D3 or by 1,25(OH)2D3-induced slight hypercalcemia may also contribute to the reduction of resorption surface with osteoclasts." (PMID 25315028, 2014). "It is a concern that chronic use of PTH may lead to hypercalcemia." (PMID 24503654, 2014). "Furthermore, additional studies suggest an association between elevated parathyroid hormone levels and cognitive deficits in the absence of hypercalcemia." (PMID 25505674, 2013). "Interestingly, in a community-based cohort of elderly men, higher (and high normal) plasma PTH levels were associated with a higher risk of cardiovascular mortality in the absence of hypercalcemia." (PMID 25505674, 2013). "However, the LVH in PHPT may be related to hypercalcemia secondary autonomous overproduction of PTH." (PMID 22719761, 2012). "The patient had a high normal serum level of 1,25-dihydroxyvitamin D and a suppressed parathyroid hormone value, an indication that the hypercalcemia was not mediated by parathyroid hormone and might be associated with 1,25-dihydroxyvitamin D." (PMID 18691418, 2008). "Primary hyperparathyroidism (PHPT) is a common endocrine disorder characterized by a condition in which one or more parathyroid glands are overactive, leading to excessive release of parathyroid hormone (PTH) and hypercalcemia." (PMID 41473886, 2026). "Primary hyperparathyroidism (pHPT) is an endocrine disorder characterized by excessive secretion of parathyroid hormone (PTH), often leading to hypercalcemia." (PMID 41066026, 2026).
Hypercalcemia (continued). "Primary hyperparathyroidism (pHPT) is a relatively common disorder characterized by the excessive secretion of parathyroid hormone (PTH), leading to hypercalcemia, hypophosphatemia, and osteoporosis." (PMID 40727913, 2025). "Measurement of total and ionized calcium levels, along with parathyroid hormone (PTH), helps diagnose hyperparathyroidism in patients with hypercalcemia." (PMID 40540009, 2025). "Primary hyperparathyroidism (PHPT) is characterized by excessive parathyroid hormone (PTH) secretion, leading to hypercalcemia and hypophosphatemia." (PMID 40104290, 2025). "Persistent disease was defined as failure to normalize calcium and parathyroid hormone (PTH) within six months of index surgery, and recurrent disease was defined as return of hypercalcemia after at least six months of normocalcemia." (PMID 41030731, 2025). "In cases where PTH levels remain elevated without hypercalcemia or an identifiable secondary cause, the condition is termed normocalcemic primary hyperparathyroidism (NPHPT), an increasingly recognized variant that may still confer skeletal and cardiovascular risk." (PMID 41301518, 2025). "After surgery, serum calcium increased again (iCa2+ 1.48 mmol/L with high parathyroid hormone (PTH) 39 ng/L, n = 5.5–38.4), and he subsequently received cinacalcet to treat hypercalcemia." (PMID 40231466, 2025). "Primary hyperparathyroidism (PHPT) is a disorder characterized by excessive secretion of parathyroid hormone (PTH), commonly leading to hypercalcemia." (PMID 40731865, 2025). "More than half of the cases (61.53%) were diagnosed incidentally, with common biochemical findings including elevated parathyroid hormone (PTH) levels (median: 430 pg/mL) and hypercalcemia in 80% of the patients." (PMID 40142758, 2025). "Primary hyperparathyroidism (pHPT) is characterised by excessive secretion of parathyroid hormone (PTH), resulting in serum hypercalcaemia." (PMID 39733582, 2025). "Laboratory investigations revealed elevated parathyroid hormone (PTH) levels at 99.6 pg/ml and hypercalcemia at 11.5 mg/dl, with serum phosphorus at 2.25 mg/dl." (PMID 39427404, 2024). "Our cases presented with pathological fractures, moderate pain, multiple lytic lesions, severe hypercalcaemia, increased ALP (alkaline phosphatase) and PTH (parathyroid hormone)." (PMID 39213924, 2024). "At transplantation, only 5.7% (n = 69) of patients had normal PTH values, whereas 32.7% (n = 396) had secondary HPT without hypercalcemia and 37.0% (n = 448) had secondary HPT with hypercalcemia." (PMID 39001249, 2024). "The release of the parathyroid hormone (PTH) enhances calcium resorption from the bone and increases absorption in the small intestine, resulting in hypercalcaemia and excess ionized calcium in the body." (PMID 38338159, 2024). "At transplantation, living donor KTRs had a significantly higher rate of normal PTH and a higher rate of HPT with hypercalcemia than deceased donor KTRs." (PMID 39001249, 2024). "We report four cases that experience pathological fractures with moderate pain, multiple lytic lesions, severe hypercalcemia, increased ALP (Alkaline Phosphatase), and PTH (Parathyroid Hormone)." (PMID 39213924, 2024). "The patient had very high PTH levels (1911 pg/mL), elevated alkaline phosphatase (ALP = 161 U/L), and mild hypercalcemia (10.4 mg/dL)." (PMID 38893652, 2024). "Primary hyperparathyroidism, predominantly caused by parathyroid adenomas, is a common endocrine disorder characterized by excessive secretion of parathyroid hormone (PTH), leading to hypercalcemia." (PMID 39427404, 2024). "It usually induces elevated serum calcium and parathyroid hormone (PTH) levels and the clinical presentation is often characterized by severe symptoms of hypercalcemia." (PMID 37397577, 2023). "The observation of hypercalcemia should promptly raise the possibility of PHPT, which should be confirmed with PTH measurements." (PMID 37252701, 2023).
Hypercalcemia (continued). "Pancreatitis in the absence of additional risk factors such as gallstones and alcohol abuse along with raised parathyroid hormone (PTH), hypercalcemia and osteolytic bone lesions led us towards the diagnosis of PHPT." (PMID 37519515, 2023). "In order to adapt to the persistently increased PTH level, parathyroid cells undergo uncontrolled proliferation developing PTA and hypercalcemia." (PMID 36755240, 2023). "Indeed, hypercalcemia can be encountered in HT, mainly associated with subcutaneous fat necrosis (SFN), even though this condition may be normocalcemic or even hypocalcemic in a much lower percentage of cases, due to an immature PTH response." (PMID 37929024, 2023). "However, if high PO4 concentration could suppress CaR activity completely, thus acting effectively as a potent calcilytic, then the additional PTH-induced phosphaturia would resolve the hyperphosphataemia but would worsen the hypercalcaemia, perhaps even dangerously so." (PMID 37064904, 2023). "Elevated calcitriol level (142 pg/mL) and low parathyroid hormone (PTH) and parathyroid hormone-related protein (PTHrP) have been detected, suggesting that the hypercalcemia has been mediated by the elevation of calcitriol levels." (PMID 36672478, 2023). "Given the relative stability of calcitriol and persistent hypercalcemia, decreased expression of CYP27B1 likely reflects low PTH levels." (PMID 37311769, 2023). "Laboratory investigations showed elevated parathyroid hormone (PTH) and serum calcium levels (PTH-dependent hypercalcemia)." (PMID 37041908, 2023). "In PHPT, primary abnormal parathyroid tumors inappropriately secret excessive parathyroid hormone (PTH) and thus lead to hypercalcaemia and a series of symptoms." (PMID 36777354, 2023). "Hyperparathyroidism is a common endocrine disorder characterized by elevated blood concentration of parathyroid hormone (PTH) and hypercalcemia, usually due to a benign adenoma." (PMID 35379205, 2022). "Experimental hypercalcemia was induced by calcium gluconate injection in thyro-parathyroidectomized (T-PTX) VDR +/+ and VDR−/− mice with constant PTH infusion." (PMID 35807756, 2022). "PTH-rP and HHM are particularly relevant in the setting of hypercalcemia of malignancy, accounting for at least 80% of cases, with some studies attributing it to nearly 90% to 100% of cases." (PMID 35481321, 2022). "Malignancies may lead to hypercalcemia through efflux of calcium from the skeleton either through bone metastases (often lung or breast cancer) or through the production of substances that may mimic PTH (PTHrP), often seen in hematological malignancies such as multiple myeloma or lymphomas." (PMID 36547749, 2022). "PCs are a group of rare malignancies that are often characterized by vastly elevated serum parathyroid hormone (PTH) and are frequently comorbid with severe hypercalcemia, also known as malignant hypercalcemia." (PMID 35846299, 2022). "Acute worsening of hypercalcemia in patients with chronic primary hyperparathyroidism can be challenging, and availability bias may mislead physicians to diagnose worsening primary hyperparathyroidism, especially if the parathyroid hormone is also trending higher." (PMID 36505117, 2022). "This role of PTH is attributed to its structural similarity of 15–25 amino acids to 1–11 amino acids of ACTH and the indirect effect of hypercalcemia." (PMID 35974370, 2022). "As a consequence of cyclin D1 over-expression, mutated mice developed enlarged hyperplastic parathyroid glands, characterized by increased cell proliferation and enhanced PTH secretion, and manifested a chronic PHPT with hypercalcemia and bone abnormalities." (PMID 35282432, 2022). "Although PTH stimulates an increase in tubular magnesium reabsorption in patients with PHPT, hypercalcemia has the opposite effect." (PMID 34416890, 2021).